GFI1 (growth factor independent 1 transcriptional repressor)
Diseases named in the same sentence as GFI1 in open-access papers (continued):
Sharing a sentence is not in itself a finding about the gene and the disease.
neutropenia (20 papers, 2013 to 2025). A decrease in the number of neutrophils found in the blood. "Gfi1 is essential for the differentiation and survival of neutrophils, as evidenced by the severe neutropenia observed in Gfi1‐deficient mice." (PMID 39845896, 2025). "Growth factor independent 1 transcriptional repressor (GFI1) germline variants have been reported in four patients with neutropenia; inheritance patterns were consistent with an AD mode of inheritance." (PMID 32066420, 2020). "Congenital neutropenia and monocytosis due to GFI1 variants was first reported in 2003, following the observation that GFI1-deficient mice were unexpectedly neutropenic." (PMID 32066420, 2020). "The constitutive neutropenia in Gfi-1-deficient mice can, to a certain extent and for a short period of time, be compensated by the adoptive transfer of neutrophils or their precursors." (PMID 32038641, 2019). "PRDM5 is in fact able to interact with Growth factor independent 1 (Gfi1) transcription factor, essential for hematopoiesis, whose inactivation impaired blood cell formation, causing neutropenia and lymphopenia and release from bone marrow of immature cells." (PMID 24832654, 2013). "Other rare genetic disorders of neutropenia are GFI1, WAS, SDBS, and G6PC3 mutations." (PMID 37993852, 2023). "The growth factor independent 1 transcriptional repressor gene (GFI1) is most highly expressed in the bone marrow and has been associated with immune system disruption, and conditions such as haematopoiesis, neutropenia, leukaemia and prostate cancer among others." (PMID 30215712, 2019). "This phenotype strongly overlaps with that of Gfi1 knock-out mouse models (Gfi1-ko/ko) showing defects of the adaptive and innate immune system such as reduced lymphocyte numbers, neutropenia, and immature monocyte accumulation." (PMID 29879182, 2018). "Besides severe neutropenia, Gfi1-deficient mice also show various defects in the T and B cell compartment and have a median survival time of ∼8–10 wk, in line with the severe neutropenia and lymphocyte defects caused by dominant negative GFI1 mutations in human patients." (PMID 30464050, 2018). "Here, we utilize Gfi1-ko/ko mice as model for severe congenital neutropenia to assess the cellular and molecular mechanisms leading to low bone mass." (PMID 29879182, 2018). "In a chronic inflammatory condition (SPF) Gfi1 neutropenia mildly favors osteoclastogenesis but only a boosted inflammation (SPF+nonSPF) efficiently stimulates osteoclast formation and activity." (PMID 29879182, 2018). "As Gfi1 knockout mice display neutropenia, KM cytospins were prepared to examine neutrophil granulocytes in qmc551 homozygous fish." (PMID 27432513, 2016). "Broadly, these conditions can be divided into those where neutropenia is the predominating feature, such as in ELANE, GFI1, HAX1, CSF3R and WAS mutations and those where neutropenia is part of a multi-system disorder." (PMID 23758768, 2013). "It has been shown that absence of Gfi1 in mice or disabling mutations in the human GFI1 gene leads to neutropenia and accumulation of monocyte and monocytic precursors." (PMID 29925903, 2019). "Due to neutropenia Gfi1-ko/ko mice expose signs of systemic inflammation." (PMID 29879182, 2018). "Gfi1, a downstream target of SH-2251, is broadly expressed in hematopoietic lineage cells, and Gfi1 knockout animals display many abnormalities, including neutropenia, T cell development defects, hematopoietic stem cell defects and defects in dendritic cell development and functions." (PMID 23613936, 2013). "It would be interesting to explore whether in vivo administration of Mek1/2 inhibitors alleviates neutropenia in Gfi1−/− mice; if it does, suppression of Erk1/2 signaling could represent a novel therapeutic approach in the treatment of SCN patients with GFI1 mutations." (PMID 30679703, 2019).
neutropenia (continued). "Using Gfi1 knock-out mice (Gfi1-ko/ko) as SCN model, we studied the relationship between neutropenia and bone mass upon different pathogen load conditions." (PMID 29879182, 2018). "Patients with GFI1 and WAS gain of function (GOF) mutations are very rare and seem to present with mild to moderate neutropenia, and there are no reports on alloHSCT in these patients." (PMID 31709206, 2019). "Homozygous Gfi1GFP/GFP mice show a severe neutropenia and additional defects in the B- and T-cell lineages and in the hematopoietic stem cell fraction while heterozygous Gfi1+/GFP littermates are indistinguishable from wild type mice." (PMID 28769107, 2017). "Interestingly, GFI1 recruits to chromatin the enzyme lysine-specific demethylase-1 (LSD1); pharmacologic inhibition of LSD1 or genetic knock-down of LSD1 skews granulocyte-monocyte progenitor differentiation resulting in neutropenia and monocytosis as seen in this family." (PMID 32066420, 2020).
acute myeloid leukemia (19 papers, 2016 to 2025). Acute myeloid leukemia (AML) is a group of neoplasms arising from precursor cells committed to the myeloid cell-line differentiation. "The presence of the GFI1-36N gene variant is associated with a reduced DNA repair capacity favoring myeloid leukemogenesis and leads to an inferior prognosis of acute myeloid leukemia (AML) patients." (PMID 39857691, 2025). "A variant form of the GFI1 gene (denominated GFI136N) is associated with a predisposition to develop de novo acute myeloid leukemia (AML), but it has also been reported to be involved in a case of neutropenia." (PMID 27080012, 2016). "A single nucleotide polymorphism of GFI1, GFI1-36N, has a prevalence of 7% in healthy Caucasians and 15% in acute myeloid leukemia (AML) patients, hence most probably predisposing to AML." (PMID 36003783, 2022). "The SNP, rs34631763, in the Gfi1 gene exon was considered to be associated with acute myeloid leukemia (AML) risk in humans." (PMID 31013831, 2019). "Notably, its prevalence increases to up to 15% among patients with myelodysplastic syndrome (MDS) and acute myeloid leukemia (AML), suggesting that the GFI1-36N variant is implicated in the pathogenesis of MDS and AML." (PMID 39857691, 2025). "Recently it has been shown that reduced expression of GFI1 in blast cells of myeloproliferative neoplasm (MPN), chronic myeloid leukemia (CML) and acute myeloid leukemia (AML) patients are associated with an inferior prognosis and event-free survival." (PMID 37091981, 2023). "In 2016, Jiang et al43 demonstrated that in acute myeloid leukemia, miR-22 was suppressed through epigenetic repression involving TET1, along with SIN3 transcription regulator family member A (SIN3A), EZH2, and growth factor independent 1 (GFI1), as well as DNA copy-number loss." (PMID 40520993, 2025). "In Acute Myeloid Leukemia (AML), cancer cells induce the differentiation and polarization of monocytes into LAMs via Gfi1, a transcription factor involved in macrophage development." (PMID 37143666, 2023). "miR-196b, HOXA9, GFI1, and PIM1 are key factors involved in cellular signaling pathways that contribute to the pathogenesis of malignancies, including acute myeloblastic leukemia (AML)." (PMID 40746924, 2025). "Several studies have demonstrated the involvement of GFI1 in haematological malignancies and have suggested that low expression of GFI1 is a negative indicator of disease progression for both myelodysplastic syndromes (MDS) and acute myeloid leukaemia (AML)." (PMID 28894287, 2017). "The N-terminal SNAG domain of the transcriptional repressor GFI1 binds to the CoREST transcriptional complex proteins LSD1 and RCOR1 at the enhancers of transcription factor genes, such as SPI1 (PU.1), CEBPA and IRF8 which are important for acute myeloid leukemia cell differentiation." (PMID 38135679, 2023). "Gfi1 gain of function has been found in chronic myeloid leukemia (CML) and acute myeloid leukemia (AML) suggesting that Gfi1 is an oncogene in this tumor types." (PMID 32630147, 2020). "Other events such as the overexpression of Bcl-2 or a mutated and activated form of Kras are required to provoke an MPN like disease that can progress to acute myeloid leukemia (AML) in the absence of Gfi1." (PMID 29925903, 2019). "In recent years, a number of publications have provided evidence that GFI1 is involved in the pathogenesis of acute myeloid leukemia (AML), its proposed precursor, myelodysplastic syndrome (MDS), and possibly also in the progression from MDS to AML." (PMID 31508375, 2019). "In the referred model of retinoic acid-induced differentiation of acute myeloid leukemia cells LSD1 played a scaffolding role, and LSD1 inhibition impeded the interaction between LSD1 and GFI1, but not with HDAC1/2 and RCOR1." (PMID 34572113, 2021).
congenital neutropenia (12 papers, 2011 to 2023). "Based on its expression pattern GFI1 plays an important role in granulocytic differentiation and germline mutations in GFI1 are associated with severe congenital neutropenia." (PMID 36969082, 2023). "Mutations in GFI1 cause severe congenital neutropenia and GFI1 expression levels have been variably linked to prognosis in AML according to disease subtype." (PMID 36171271, 2022). "We identified a previously reported variant underlying congenital neutropenia in GFI1 (NM_005263.5, c.1145A > G/p.Asn382Ser, N382S)." (PMID 32066420, 2020). "Knockout (KO) mice have shown that Gfi1 is essential for neutrophil differentiation; consistently, in humans, severe congenital neutropenia is associated with GFI1 mutations." (PMID 28401061, 2017). "In humans, GFI1 mutations are associated with severe congenital neutropenia." (PMID 28401061, 2017). "Mutations in the gene that codify for Gfi1 are associated with Severe Congenital Neutropenia (SCN)." (PMID 32630147, 2020). "This group includes congenital neutropenia caused by mutations in ELANE, GFI1, HAX1, WAS (X-linked neutropenia), CSF3R, and SRP54 genes." (PMID 31709206, 2019). "A mutation in GFI1 causes severe congenital neutropenia (SCN)." (PMID 24454381, 2013). "Mutations in GFI1 gene can result in severe congenital neutropenia (SCN), and nonimmune chronic idiopathic neutropenia of adults in an autosomal dominant manner, which enhances the predisposition to leukemias." (PMID 34351909, 2021). "Bone marrow cells from a GFI1-mutant severe congenital neutropenia (SCN) patient and Gfi1−/− mice display overexpression of miR-21." (PMID 31139230, 2019). "Mutations of GFI-1 in humans were recently shown to correlate with severe congenital neutropenia (SCN) and non-immune chronic idiopathic neutropenia in adults (NI-CINA)." (PMID 38239528, 2023). "Indeed, mutation of the only transcription factor (GFI1) known to be involved in congenital neutropenia may not directly affect the transcription process but interfere with interaction with ELANE protein." (PMID 21595885, 2011).
myeloma (12 papers, 2014 to 2025). "Since GFI1 is implicated in B cell maturation and plasma cell (PC) development, we examined its prevalence in patients with multiple myeloma (MM), a haematological malignancy characterized by expansion of clonal PCs." (PMID 34760702, 2021). "As previously shown, Gfi1 could protect hematopoietic stem cells and multiple myeloma cells via suppressing cell death-related genes, conversely, Gfi1 deficiency contributed to increased cell death." (PMID 40787173, 2025). "Hence it would be conceivable that the presence of GFI1-36N might not only disturb myeloid development but also B-cell development and predispose to myeloma development." (PMID 34760702, 2021). "However it could be that GFI1-36N is a general factor predisposing to development of myeloid malignancies and myeloma." (PMID 34760702, 2021). "Proof of Gfi1-mediated chromatin’s suppression of RUNX2 in the ambit of myeloma suppression derived from the demonstration that the boost of Gfi1 in preOBs blocked RUNX2 reporter expression." (PMID 35681577, 2022). "Conversely, Gfi1 overexpression in mouse multiple myeloma cells enhanced bone destruction by increasing osteoclast number and size, thereby promoting tumor growth." (PMID 36077242, 2022). "Univariant analysis of the IA15 myeloma dataset from the MMRF database for the association of GFI1 gene expression and overall survival showed that high GFI1 was significantly associated with shorter overall survival." (PMID 35159039, 2022). "Changes in gene expression of GFI1-36N homo- or heterozygous myeloma cells as compared to GFI1-36S homozygous cells." (PMID 34760702, 2021). "Knockdown of GFI1 in multiple myeloma cells was sufficient to reverse the recruitment of EZH2 and HDAC1, increase RUNX2 expression, and rescue osteoblast differentiation." (PMID 29867053, 2018). "Therefore, it would be informative to conduct a genomewide Gfi1 chromatin immune precipitation (ChIP) analyses coupled with total RNA sequencing to define the spatial‐temporal nature of the myeloma‐inducible Gfi1 regulatory cistrome in MM‐BMSCs." (PMID 30918921, 2019). "Interestingly, in the myeloma context, Gfi1 has recently been pointed out as a new transcriptional repressor of Runx2, blocking OB differentiation and being increased both in MSCs from MM patients and MM-bearing mice." (PMID 25268740, 2014). "An earlier study has shown that transcriptional repressor GFI1 negatively regulates the expression of SGPP1 and that GFI1-dependent SGPP1 repression promotes growth and survival of multiple myeloma cells." (PMID 34235182, 2021).
myeloproliferative disease (11 papers, 2012 to 2024). "A recent study described that Gfi1 loss of function induced the progression of myeloproliferative disorder (MPD) to AML in a K-ras mouse model." (PMID 29147018, 2017). "In combination with inhibition of apoptosis, the increased production of reactive oxygen species (ROS) observed in GFI1 KD mice may contribute to the onset of myeloproliferative disorders that can progress into myeloid leukemia." (PMID 31649884, 2019). "In mice, both Gfi1 KD and KO resulted in increased immature myeloid cell numbers which transformed to a myeloproliferative disease in Gfi1 KD but not KO mice." (PMID 31649884, 2019). "Considering the role of GFI1 in myeloid development, GFI136N status could also be of prognostic value for patients with myeloproliferative diseases and chronic myeloid leukemia." (PMID 27080012, 2016). "This analysis focused on genes (Srpk2, Hes1, Mtor, Pdp1, Meis1, Gfi1, Foxo3, Stra13, Hif1α, and Cebpε) involved in HSC proliferation; maintenance of quiescence, growth, and stem cell exhaustion; and development of myeloproliferative disorder in young and geriatric mice." (PMID 27366154, 2016).
lymphoma (10 papers, 2014 to 2024). A malignant (clonal) proliferation of B- lymphocytes or T- lymphocytes which involves the lymph nodes, bone marrow and/or extranodal sites. "Combinational overexpression of Gfi1 and c-Myc considerably accelerated lymphoma development whereas loss of Gfi1 led to lymphoma regression in Eμ-Myc transgenic mice, indicating an important role of Gfi1 in the initiation and maintenance of c-Myc-driven lymphoma development." (PMID 33051558, 2020). "The anti-apoptotic activity of Gfi1 is also critical for its oncogenic potential in lymphoid leukemia and lymphoma." (PMID 39374784, 2024). "Further, Gfi1 cooperates with oncoproteins, such as Myc and Pim-1, to induce development of lymphoma and ALL." (PMID 30286780, 2018). "A similar accelerated rate of lymphoma development was observed when lck-gfi1 mice were crossed with mice that carried an L-myc gene that was targeted to be expressed at high levels in T-cells." (PMID 24860787, 2014). "Gfi1 expression is increased in human lymphoma and acute lymphoblastic leukemia cells." (PMID 33051558, 2020). "Additionally, retroviral insertions in the ice1/gfi1/pal1/evi5 locus were observed in nearly 80% of the lymphomas." (PMID 24860787, 2014). "GFI-1, Sin3A, PRMT5 and CCAR2 genes were uniformly expressed at high levels also in SUP-M2 cells, thus confirming their potential relevance in lymphoma." (PMID 39478125, 2024). "A second RIM/DS screen comparing lymphomas of wild-type and parental transgenics showed that CD2-MYC tumours are virtually dependent on activation of Runx family genes in strong preference to other potent Myc collaborating genes (Gfi1, Notch1)." (PMID 24586197, 2014).
acute lymphoblastic leukemia (7 papers, 2013 to 2022). Leukemia with an acute onset, characterized by the presence of lymphoblasts in the bone marrow and the peripheral blood. "Besides regulating normal hematopoiesis, high levels of GFI1 have been associated with supporting the viability of both types of acute lymphoblastic leukemia (ALL) in the presence of initiating oncogenes." (PMID 35159039, 2022). "We have further demonstrated that GFI1 acts to inhibit cell death induced by DNA damage, consistent with recent reports that Gfi1−/− HSCs and lymphoblastic leukemia cells exhibited increased rates of apoptosis in response to DNA damage." (PMID 24023884, 2013). "In contrast, mice were cured from acute lymphoblastic leukemia (ALL) following Gfi1 ablation." (PMID 33051558, 2020). "In contrast, Gfi1 ablation cured mice from acute lymphoblastic leukemia (ALL) and limited the expansion of primary T-cell ALL xenografts in mice." (PMID 24023884, 2013). "The transcriptional repressor Gfi1 can be a so-called “oncorequisite” factor that is required for the development and maintenance of lymphoid neoplasia, such as Acute Lymphoblastic Leukemia (ALL), but does not have a direct role in the ontogeny of the disease." (PMID 23528269, 2013).
deafness (7 papers, 2014 to 2024). An inherited or acquired condition characterized by the complete loss of the ability to hear from one or both ears. "All three have been implicated in hearing and deafness, Gfi1 in particular; the hair cells of mice homozygous for a Gfi1 knockout allele degenerate around P010." (PMID 26988146, 2016). "This mutation alters the function of miR-96 and their consequent gene expression profile in the mouse organ of Corti such as oncomodulin (Ocm), prestin (Slc26a5), and growth factor independent 1(Gfi1) which have been known to result in deafness and hair cell degeneration." (PMID 35546217, 2022). "Moreover, the expression levels of the other nine deafness-related genes (Myo15, Gfi1, Lhx3, Barhl1, Pjvk, Tomt, Pou4f3, Tmc1, and Grxcr2) were downregulated more than 2-fold in DT-treated Prestin-hDTR mice." (PMID 30918314, 2019). "Results of the ABRs showed that the Gfi1-NICD mutants showed no responses to even the highest levels of sound (80 dB SPL), indicating profound deafness." (PMID 25264928, 2014).